TLR3 (toll like receptor 3)
Diseases named in the same sentence as TLR3 in open-access papers (continued):
Sharing a sentence is not in itself a finding about the gene and the disease.
Immunodeficiency (12 papers, 2015 to 2024). Failure of the immune system to protect the body adequately from infection, due to the absence or insufficiency of some component process or substance. "This is evident from patients suffering from host immune deficiencies (such as mutations in TLR3 and Unc93b), which can lead to dissemination of the virus throughout the body." (PMID 32708188, 2020). "It should also be mentioned that immunodeficiencies involving the Toll-like receptor 3 (TLR3) pathway are well established, at least in children, to predispose to HSE." (PMID 33048220, 2021). "SHARPIN regulates TLR3-mediated innate immunity, auto inflammation and the development of immunodeficiency." (PMID 33255903, 2020). "There are two pathways associated with the immune deficiencies that lead to disease: the MyD88-IRAK4 pathway, involving all TLR family proteins except TLR3, and the TLR3-Unc93b-TRIF-TRAF3 pathway." (PMID 26063214, 2015). "Recently, a growing body of evidence indicates that TLR3 and TLR4 may be involved in psychosis with immune dysfunction including major depressive disorders and BD." (PMID 31379619, 2019). "It is an optimized Toll-like receptor 3 (TLR3) agonist and endogenous interferon (IFN) inducer in late-stage clinical development, with the ability to augment both innate and acquired immunity including cellular responses, like T cell response, in humans with immunodeficiency (HIV disease)." (PMID 34207861, 2021).
cervical carcinoma (11 papers, 2008 to 2025). A carcinoma arising from either the exocervical squamous epithelium or the endocervical glandular epithelium. "In this current study, we have shown the role of TLR3 associated with cervical cancer by computational approach." (PMID 40847033, 2025). "The selection criteria for SNPs included their reported association with cervical cancer or their potential effects on TLR3 structure and function." (PMID 40847033, 2025). "In addition to this, C37R of TLR3 mutations has been predicted for the first time through computational analysis (dry lab) to be highly deleterious and potentially associated with cervical cancer." (PMID 40847033, 2025). "For the first time, the structural effects produced by the mentioned mutations, its interaction analysis & oncogenic nature of the TLR3 gene against Cervical Cancer investigation were performed." (PMID 40847033, 2025). "Although in silico methods cannot completely replace physical and frequently conclusive testing processes and methodologies, the current work is regarded to be useful for future research efforts that target TLR3 to treat cervical cancer." (PMID 40847033, 2025). "This study has predicted that TLR3 is related to cervical cancer with the help of the missense SNPs retrieved and the different in silico techniques involved." (PMID 40847033, 2025). "Previous studies have demonstrated that TLR3 is aberrantly expressed in several cancers, including cervical cancer." (PMID 40847033, 2025). "This study aimed to investigate the impact of TLR3 missense SNPs on cervical cancer development through in silico methods." (PMID 40847033, 2025). "According to a previous study, a reduction in TLR1 expression was detected in the malignant epithelium, and an increase in TLR3 expression was detected in the premalignant epithelium of the HPV+ cervical cancer tumor microenvironment." (PMID 39208235, 2024). "In an in vitro study using the cervical cancer cell line U14, treatment with TLR3-siRNA significantly decreased cell growth, migration and invasion." (PMID 33986756, 2021). "In our study, upregulation of TLR4 in cervical cancer was the most significant among the TLRs examined (including TLR3, TLR4, TLR7, and TLR8)." (PMID 28626766, 2017). "In this study, the level of TLR3 mRNA expression was obviously upregulated in the cervical squamous epithelial cells in the cervical cancer group." (PMID 28626766, 2017). "The in silico analysis suggests that these genetic variations may contribute to the development and progression of cervical cancer by modulating TLR3 function." (PMID 40847033, 2025). "The TLR3 gene was used as input for both uterine and cervical cancer in the following Target run." (PMID 40847033, 2025). "Therefore, our study expands on these findings by suggesting that these N284I, C37R and L360P may also contribute to oncogenic processes in cervical cancer, thereby connecting TLR3 immune dysfunction to tumor biology." (PMID 40847033, 2025). "When evaluating the gene expression patterns of TLR transcripts, specifically TLR1, TLR3, TLR4, TLR6, TLR7, TLR8 and TLR10, in HPV+ and HPV- cervical cancer tissue samples, we observed an increase in TLR4 expression and a decrease in TLR1 and TLR3 expression." (PMID 39208235, 2024). "In our study, the expression levels of TLR3, TLR4, TLR7, TLR8, NF-κB p65, and iNOS mRNA in the cervical squamous epithelial cells were significantly higher in the cervical cancer group than in the HR-HPV patients and healthy controls." (PMID 28626766, 2017). "The number of patients was too low (less than 10) to make any conclusions, and TLR3 was unable to change the expression of the nearby gene, hence there were no results for cervical cancer presented in the database." (PMID 40847033, 2025).
cervical carcinoma (continued). "The effect of ectopic expression of SORBS2, TLR3, CYP4V2, FBXO18, IL15RA, WDR37 and DIP2C on the cell phenotype, in particular senescence, was investigated in primary cells, HPV-immortalized cells and cervical carcinoma cells." (PMID 24165198, 2013). "Thus, although TLR4 is considered an important marker of HPV+ cervical cancer, alterations in the levels of TLR1, TLR3 and TLR6 observed in HPV+ samples may be the target of investigations related to the tumor inflammatory process." (PMID 39208235, 2024). "We tested the TLR3, TLR4, TLR7, TLR8, NF-κB p65, and iNOS mRNA expression levels in the cervical tissue epithelial cells of the three groups and found that all mRNA levels were higher in the cervical cancer group than in the HR-HPV group and control group (P < 0.05)." (PMID 28626766, 2017).
depression (11 papers, 2013 to 2023). "Lastly, our study was unable to evaluate some immune markers and cytokines previously linked to WNV infection such as IL-2, IL-4, IFN-B, TLR-3, IL-11, and IL-18, as well as some previously linked to depression such as IL-18 and NFκB." (PMID 35745504, 2022). "A variety of proinflammatory cytokines such as IL-1β, IL-6, TNF, and Toll-like receptor 3 (TLR3) has been found to overexpress depression." (PMID 34650925, 2021). "Interferon-α (IFN-α) potentiates immune responses against viral pathogens that induce toll-like receptor-3 (TLR3) activation but evokes severe major depressive disorder in humans by mechanisms that remain insufficiently described." (PMID 32504419, 2020). "The viral mimic polyinosinic-polycytidilic acid, Poly I:C is a synthetic double-stranded RNA which activates the Toll-like receptor 3 (TLR3) pathway, and which is used in animal model of depression." (PMID 30042304, 2018). "Moreover, the activation of TLR3 reduced anxiety and depression and increased spontaneous activity in the AD mice." (PMID 36797783, 2023). "Thus, with the aim to analyze synergistic phenomena that may underlie the interferon-related depression in HCV patients both simulations, IFN treatment and TLR3 stimulation, were studied together in vitro in murine neurons." (PMID 24391741, 2013). "Both TLR3 and TLR4, have been found in post-mortem brain samples from individuals with depression that died by suicide that suffered from depression." (PMID 31647818, 2019). "Moreover, suicide victims with depression showed higher levels of IL-1β, IL-6 and TNF in postmortem brains, while the receptors for the production of these cytokines, such as Toll-like receptor 3 (TLR3) and TLR4, were also affected." (PMID 34827513, 2021). "Additionally, increased expression of a variety of innate immune genes and proteins, including IL-1β, IL-6, TNF, Toll-like receptor 3 (TLR3) and TLR4, has been found in post-mortem brain samples from individuals with depression that died by suicide." (PMID 31647818, 2019). "The mRNA expression of TLR3 and TLR4 has been found to increase in the prefrontal cortical regions of individuals with depression that died by suicide and depressed non-suicide subjects." (PMID 31647818, 2019).
esophageal squamous cell carcinoma (11 papers, 2014 to 2025). Esophageal squamous cell carcinoma (ESCC) is a type of esophageal carcinoma (EC) that can affect any part of the esophagus, but is usually located in the upper or middle third. "High TLR3, 4, and 9 expression in esophageal squamous cell carcinoma cells have been associated with lymph node metastasis and TLR7 and 9 expression to worse histological grade." (PMID 24847326, 2014). "For example, in esophageal cancer, increased expression of TLR3, TLR4, TLR7, and TLR9 has been linked to esophageal squamous cell carcinomas, while TLR1, TLR2, TLR4, and TLR6 are often overexpressed in esophageal adenocarcinoma." (PMID 40109582, 2025). "Examples are the overexpression of TLR3 in monocytes of Kaposi’s sarcoma patients or the overexpression of TLR3, 4, 7, and 9 in tumor cells of patients affected by esophageal squamous cell carcinoma." (PMID 36672572, 2022). "A variety of TLRs, including TLR3, 4, 7, and 9, have been shown to be overexpressed in esophageal squamous cell carcinoma, when compared to normal esophagus." (PMID 24847326, 2014). "A variety of TLRs such as TLR3 and TLR5 have been shown to be overexpressed in esophageal squamous cell carcinoma and esophageal adenocarcinoma." (PMID 34795689, 2021). "Therefore, it is reasonable to speculate that the high expression of TLR3 in KIRC tissues may be an active immune response, which is consistent with the conclusion of a recent study on esophageal squamous cell carcinoma." (PMID 36419829, 2022). "We previously reported that high tumoral expression of Toll-like receptor 3 (TLR3) and CXCL10, a member of the CXC chemokine family, was an independent positive prognostic factor in patients with advanced thoracic esophageal squamous cell carcinoma (ESCC)." (PMID 40029556, 2025).
microcephaly (11 papers, 2016 to 2023). A congenital or acquired developmental disorder in which the circumference of the head is smaller than normal for the person's age and sex. "They found that ZIKV could perturb cell fate and attenuate organoid growth by increasing activation of the innate immune receptor, Toll-like-Receptor 3 (TLR3), which could affect the apoptosis and neurogenesis pathways and play a key role in causing microcephaly." (PMID 27775637, 2016). "In 10 day old cerebral organoids, ZIKV-mediated microcephaly was dependent on Toll-like receptor 3 (TLR3) overactivation." (PMID 35337041, 2022). "Human embryonic stem cell-derived cerebral organoids were used to identify a connection between ZIKV Toll-like receptor-3 activation and microcephaly." (PMID 29194359, 2017). "Therefore, ZIKV-mediated TLR3 activation likely participates in the mechanistic control of the neurogenesis disruption that leads to serious neurological disorders, including microcephaly, in newborns." (PMID 36831177, 2023). "TLR3 was shown to be activated by ZIKV in human organoid cells and in murine neurospheres, causing perturbation of 41 genes related to neurodevelopment and reducing the organoid volume as seen in clinical microcephaly." (PMID 30374352, 2018). "Therefore, further studies will be required in order to clarify a causal relationship between TLR3-mediated innate immune response and ZIKV-induced microcephaly." (PMID 28822354, 2017). "Intriguingly, both ZIKV and dengue virus, members of the flavivirus genus, have been shown to lead to activation of innate immune responses and increase the expression of TLR3; however, only ZIKV would cause microcephaly and induce the adverse effects observed in 3D organoid culture." (PMID 28822354, 2017). "Brain organoids recapitulated microcephaly disease and, when infected with ZIKV, it induced Toll-like-Receptor 3 activation, a decrease in organoid size, resembling microcephaly, which, in turn, is linked to the number of viral copies." (PMID 36980271, 2023).
non-small cell lung carcinoma (11 papers, 2018 to 2025). A group of at least three distinct histological types of lung cancer, including non-small cell squamous cell carcinoma, adenocarcinoma, and large cell carcinoma. "However, several reports also demonstrated that TLR3 protein level on tumor cells was associated with improving overall survival in a stage-I cohort study of non-small cell lung cancer." (PMID 34094905, 2021). "Reciprocally, TLR3 expression induces cellular programmed death in non-small-cell lung cancer (NSCLC) and androgen-sensitive prostate cancer." (PMID 35000541, 2022). "While most TLRs, such as TLR2, TLR4, TLR5, TLR7, and TLR9, play dual roles in carcinogenesis, TLR1 and TLR3 are largely tumor-suppressive, as demonstrated by induced apoptosis by TLR3 in human non-small-cell lung cancer cells." (PMID 36551308, 2022). "Francesca revealed that TLR3 could induce apoptpsis in Non-Small-Cell Lung Cancer via boosting the innate immune response." (PMID 34266404, 2021). "In addition, some studies support the use of TLR3 agonists in patients with non-small cell lung cancer (NSCLC) to reactivate the local innate immune response." (PMID 33796026, 2021). "A clinical trial showed that Poly-ICLC (Hiltinol), an advanced form of TLR3 agonist, could kill cancer cells and inhibit the metastasis of non-small cell lung cancer by activating several cancer suppressors and rebuilding an immunosuppressive tumor microenvironment." (PMID 34094905, 2021).
Alzheimer disease (10 papers, 2018 to 2024). A progressive, neurodegenerative disease characterized by loss of function and death of nerve cells in several areas of the brain leading to loss of cognitive function such as memory and language. "This SNP locates at the intergenic region between SORBS2 and TLR3 at Chromosome 4 and are 72k downstream of SNP rs75718659, which was reported associated with Alzheimer’s disease in a family-based GWAS." (PMID 30133451, 2018). "However, when poly(I:C) was injected intraperitoneally into the APP/PS1 mouse model of Alzheimer’s disease (AD), activation of TLR3 attenuated neuronal loss and inhibited the activation of microglia and astrocytes, decreasing the expression of proinflammatory mediators in the hippocampus." (PMID 37124206, 2023). "Administration of the dsRNA polymer to animals of age 4 to 9 months induces TLR3 responses that are protective in the APPswe/PSEN1dE9 transgenic mouse model of Alzheimer’s disease (AD)." (PMID 39371608, 2024). "TLR3 expression has been positively correlated with plaques in Alzheimer disease as well as colocalising with the phagocytic marker CD68." (PMID 36120803, 2023). "Toll-like receptor 3 (TLR3) plays an important role in the immune/inflammatory response in the nervous system and is a main pathological feature of Alzheimer’s disease (AD)." (PMID 36797783, 2023). "In macrophages, curli amyloid fibrils associate with DNA from damaged cells and activate intracellular TLR9 via toll-like receptor 3–mediated uptake, initiating an inflammatory response in Alzheimer's disease." (PMID 34048712, 2021). "This study is focused on the potential roles of various TLRs in various neurodegenerative diseases such as Parkinson’s disease (PD) and Alzheimer’s disease (AD), namely TLR2, TLR3, TLR4, TLR7, and TLR9 in AD and PD in human beings and a mouse model." (PMID 34827372, 2021).
brain ischemia (10 papers, 2011 to 2023). Diminished or absent blood supply to the brain caused by obstruction (thrombosis or embolism) of an artery resulting in neurologic damage. "Astrocytic TLR3 is associated with ischemic preconditioning-induced protection against brain ischemia in rodents via the stimulation of NF-κB." (PMID 29571298, 2018). "Other results showed that the therapeutic administration of poly-IC administered 30 min after cerebral ischemia markedly decreased infarct volume via TLR3-mediated prevention of Fas/FADD interaction, suggesting that poly-IC postconditioning plays a protective role against cerebral I/R injuries." (PMID 25928750, 2015). "However, in TLR3-knockout mice, the protective effect of poly-IC against cerebral ischemia disappeared." (PMID 25928750, 2015). "Our results reveal that TLR3, NF‐κB, and TNF‐α could be utilized as predictive biomarkers for poly I:C treatment against cerebral ischemia injury." (PMID 35510663, 2022). "TLR-3, -4, -6 and -9 were not significantly changed after neonatal HI, which suggests that the TLR response to cerebral ischemia differs in the adult compared to the developing brain." (PMID 21569241, 2011). "Clinical studies have shown that the expression of TLR3 and TLR9 in the peripheral blood of patients with ischemic stroke has nothing to do with nerve damage, which further indicates that TLR3 and TLR9 are not directly involved in the regulation of cerebral ischemia-reperfusion inflammation damage." (PMID 35008558, 2021).
inflammatory bowel disease (10 papers, 2015 to 2023). A spectrum of small and large bowel inflammatory diseases of unknown etiology. "Our novel observations, together with previous results from our laboratory showing that TLR3 is upregulated in inflammatory bowel disease, strongly indicate that this PRR may indeed play a role in activating the CCL20-CCR6 axis in inflammatory bowel disease." (PMID 26536229, 2015). "With these distinctive capacities, TLR3-preconditioned UC-MSC showed improved therapeutic efficacy against experimental animal models for autoimmune diseases, especially on inflammatory bowel disease (IBD)." (PMID 32928306, 2020). "T. halophilus strain KK221 strain induces INF-β through TLR3 and TLR9 on dendritic cells and contributes to the anti-inflammatory function against inflammatory bowel diseases." (PMID 30586377, 2018). "Indeed, human IECs constitutively express TLR3, TLR5, TLR9, NOD1, NOD2 and low levels of TLR2 and TLR4, where TLR4 is increased in inflammatory bowel disease (IBD) IECSs and intestinal macrophages." (PMID 36296363, 2022). "A link to human inflammatory bowel disease (IBD) is the observation that patients carrying mutations in both TLR3 and TLR7 had higher rates of hospitalisation compared with IBD patients without mutations." (PMID 28869283, 2017). "Cario and Podolsky analysed TLR2, TLR3, TLR4, and TLR5 protein levels in colonic biopsies and found that TLR4 protein levels were higher in both the inflamed and the noninflamed colonic mucosa of patients with inflammatory bowel disease compared to controls." (PMID 28246611, 2017).
nasopharyngeal carcinoma (10 papers, 2007 to 2024). A carcinoma arising from the nasopharyngeal epithelium. "For EBV, TLR3 was detected to be highly expressed in EBV-associated nasopharyngeal carcinomas (NPC) cell lines and clinical specimens." (PMID 37371120, 2023). "Here, we show that EBERs induce inflammatory response in nasopharyngeal carcinoma (NPC) cells through Toll-like receptor 3 (TLR3), mainly featured by high level of TNFα production." (PMID 26172457, 2015). "Antagonists of IAP function such as those used in this study may therefore represent a potential antitumor strategy to overcome necrosis resistance activated by TLR3 agonists for instance in Epstein-Barr virus (EBV)-induced epithelial cancers (nasopharyngeal carcinoma)." (PMID 21737330, 2011). "Surprisingly, to our knowledge, there has been no report so far about the expression of TLR3 in EBV-related nasopharyngeal carcinomas." (PMID 23198710, 2012).